MYC (MYC proto-oncogene, bHLH transcription factor)
Diseases named in the same sentence as MYC in open-access papers (continued):
Sharing a sentence is not in itself a finding about the gene and the disease.
sarcoma (70 papers, 2004 to 2026). A usually aggressive malignant neoplasm of the soft tissue or bone. "As a first step, cancer hallmarks were identified as major risk factors for survival in patients with sarcoma, including MYC targets V1 and V2." (PMID 38240704, 2024). "The results of the two-way survival analysis combined with cancer hallmarks indicated that sarcoma patients with high-risk-scores and high MYC targets Z-scores showed the lowest overall survival rates." (PMID 38240704, 2024). "Firstly, a ssGSEA and Cox-PH analysis identified MYC targets V1 and V2 as the highly associated cancer hallmarks with overall survival in sarcoma patients." (PMID 38240704, 2024). "In total, it seems that in certain sarcoma entities MYC amplification is associated with higher tumor grades and worse prognosis." (PMID 29765529, 2018). "This review aims to explore which sarcoma subtypes (BSs and STSs) are most associated with MYC overexpression and to investigate potential future therapeutic strategies highlighting MYC’s potential as a key therapeutic target and its influence on the development of future treatment strategies." (PMID 40076599, 2025). "In addition, most HRDhigh sarcoma entities exhibited enriched gene sets associated with cell cycle‐related targets of MYC and E2F transcription factors as well as gene sets involved in the G2/M checkpoint and mTORC1 signaling, some of which were also found to be upregulated in HGSOC." (PMID 36779660, 2023). "PRL can activate the JAK-STAT signalling pathway by binding to PRLR on sarcoma cells, leading to the up-regulation of c-MYC." (PMID 42083506, 2026). "In several sarcoma subtypes, MYC upregulates the transcription factor TBX3, which in turn promotes proliferation, tumor formation, migration, and invasion." (PMID 40076599, 2025). "The interplay between CDK4 and MYC forms a pivotal oncogenic axis that drives the progression of various cancers, including sarcomas." (PMID 40076599, 2025). "The low frequency of MYC gain in our advanced sarcoma patients prompted us to validate the results by ddPCR." (PMID 41514647, 2025). "Despite its well-established centrality in sarcoma pathogenesis, targeting MYC directly remains challenging due to its “undruggable” protein structure." (PMID 40076599, 2025). "MYC amplification has also proven valuable in distinguishing AS from other atypical vascular lesions or sarcoma types." (PMID 40666093, 2025). "This review underscores the importance of understanding the intricate roles of MYC across sarcoma subtypes to guide the development of effective targeted therapies." (PMID 40076599, 2025). "Targeting the MDM2/MYC axis represents a promising therapeutic strategy for OS and other sarcomas, just as what happens in myeloma." (PMID 40076599, 2025). "Disruption of this regulatory balance, such as the loss or dysfunction of MAD proteins, can result in uncontrolled MYC activity, a common feature in many cancers, including sarcomas." (PMID 40076599, 2025). "MYC plays a pivotal role in the biology of various sarcoma subtypes, acting as a key regulator of tumor growth, proliferation, and metabolic reprogramming." (PMID 40076599, 2025). "Different from previous studies, this study constructs a new sarcoma prognostic gene marker based on MYC targets V1 and V2, which adds new content to the research in this field." (PMID 38240704, 2024). "After JAK2/STAT3 inhibition, we observed a decrease in c-MYC protein expression in sarcoma cells treated with LFU and PTX combination in vitro." (PMID 36582521, 2022). "Oxygen consumption rates were also substantially increased in c-Myc-overexpressing osteogenic sarcoma cells compared to MYC-inactive osteocytes." (PMID 34503295, 2021). "Synovial sarcoma cell lines with high c-MYC protein expression were sensitive to the compound and to the gene silencing of MYC." (PMID 32429395, 2020).
sarcoma (continued). "Extended analysis of sarcomas from the TCGA archive and matched for both (MYC and PTEN) molecular alterations detected in this patient, revealed a constitutive STAT3 expression (absent in MYC amplified tumors), as also identified in prostate tumors." (PMID 31500143, 2019). "For example, brief inactivation of MYC in osteogenic sarcomas resulted in sustained regression due to differentiation of sarcoma cells into mature osteocytes." (PMID 28028012, 2017). "AOA induced cell death and decreased cell proliferation, which was rescued by DMK in the MYC-dependent osteogenic sarcoma cells." (PMID 24280108, 2013). "To understand the mechanism underlying the induction of cell death upon glucose or glutamine deprivation in MYC-dependent osteogenic sarcoma cells, we examined the levels of ROS, which can induce cell death at high levels." (PMID 24280108, 2013). "Nevertheless, the mitochondrial-targeted antioxidant Mito-Vitamin E still diminished proliferation of MYC-dependent osteogenic sarcoma cells." (PMID 24280108, 2013). "Osteocytes had a substantial increase in mitochondrial membrane potential compared to MYC-dependent osteogenic sarcoma cells." (PMID 24280108, 2013). "MYC-dependent osteogenic sarcoma cells displayed a slight elevation in glucose consumption and lactate production compared with osteocytes." (PMID 24280108, 2013). "MYC increases cell proliferation in osteogenic sarcoma cells, thereby placing a heavy demand for mitochondrial TCA cycle metabolites for macromolecule synthesis." (PMID 24280108, 2013). "Here we report metabolic changes between MYC-dependent mouse osteogenic sarcomas and differentiated osteoid cells induced upon MYC suppression." (PMID 24280108, 2013). "We analyzed cytosolic ROS and mitochondrial ROS levels with a cytosolic-targeted roGFP2 probe and a mitochondrial-targeted roGFP2 (mito-roGFP2) in MYC-dependent osteogenic sarcoma cells and osteocytes." (PMID 24280108, 2013). "While osteogenic sarcoma cells increased oxygen consumption and spare respiratory capacity upon MYC suppression, they displayed minimal changes in glucose and glutamine consumption as well as their respective contribution to the citrate pool." (PMID 24280108, 2013). "Our results showing a downregulation of CTGF in MYC-amplified AS favor its involvement in angiogenesis inhibition at least in this specific sarcoma subtype." (PMID 22383169, 2012). "However, emerging therapeutic strategies, including indirect MYC inhibition via epigenetic modulators, transcriptional machinery disruptors, and metabolic pathway inhibitors, offer new hope for sarcoma treatment." (PMID 40076599, 2025). "Previous reports suggested that MYC located on chr8 may mediate the effect of chr8 gains on patient outcome in EwS and other undifferentiated sarcomas." (PMID 41100815, 2025). "Survival analysis revealed that higher expression of SOX2, NANOG, and MYC but not OCT4 (POU5F1) or KLF4 is associated with significantly reduced survival in sarcoma patients." (PMID 36506091, 2022). "While further exploration is needed to assess the role and function of many of the amplified genes present on chromosome 8 in pediatric sarcomas, one key gene that has been highly studied in these pediatric sarcomas is MYC, which has a role in various other cancers." (PMID 30704460, 2019). "Our group could link MYC amplification to antecedent radiation treatment in angiosarcoma and various other types of radiation treated sarcoma." (PMID 29765529, 2018). "DMK in the presence of glutamine did not prevent cell cycle arrest upon doxycycline administration, suggesting that providing the end product of glutaminolysis is not sufficient to prevent cell cycle arrest that accompanies the transition of MYC-dependent osteogenic sarcoma cells into osteocytes." (PMID 24280108, 2013). "DWF provided the MYC-dependent osteogenic sarcoma cells and carefully edited the manuscript." (PMID 24280108, 2013).
sarcoma (continued). "However, diminishing mitochondrial ROS levels by using a mitochondrial-targeted vitamin E (MVE) in MYC-dependent osteogenic sarcoma cells did decrease cell proliferation." (PMID 24280108, 2013). "To test whether aminotransferases are required for glutamine-dependent increase in OCR in MYC-dependent osteogenic sarcoma cells, we utilized AOA, an inhibitor of aminotransferase activity." (PMID 24280108, 2013). "Furthermore, inhibition of aminotransferases selectively diminished cell proliferation and survival of osteogenic sarcoma MYC-expressing cells." (PMID 24280108, 2013). "Radiotherapy may act as a mediator for biological changes, such as MYC amplification in some sarcoma subgroups." (PMID 22173669, 2012). "Given MYC’s central role in tumorigenesis and progression, innovative approaches aiming at MYC inhibition could transform the therapeutic landscape for sarcoma patients, providing a much-needed avenue to overcome therapeutic resistance and improve clinical outcomes." (PMID 40076599, 2025). "Altogether, these data suggest that MYC amplification is not the hallmark of ionizing radiation in the radiation-induced sarcomas, whatever their histology might be." (PMID 22383169, 2012). "We also observed the enrichment of the E2F transcription factor (NES=2.308), MYC target (NES=2.017), and mTOR signaling (NES=1.906) in SARC sarcoma (all P < 0.05)." (PMID 40612679, 2025). "In comparison, MYC was upregulated in F9 MB-WNT that showed both MYCN and MYC high overexpression, and also in M6 high-grade sarcoma." (PMID 35978432, 2022). "RB1, a gene classified as a driver in sarcoma by COSMIC, is also well connected in our solution, linking protein kinase C inhibitor staurosporine to the seed genes MYC, SKP2 and DNMT3A." (PMID 35580047, 2022). "In summary, our work showed that EMX1 and EMX2 act as tumor suppressors by suppressing the activity of stem cell regulatory genes (OCT4, KLF4, MYC, SOX2, NANOG, NES, and PROM1) in sarcoma." (PMID 34016958, 2021). "As expected, lung tumors with driver fusions harbored mostly EML4/ALK fusions, sarcomas were driven mostly by EWSR1-related and PAX3/FOXO1 fusions, while hematologic malignancies with a spectrum of BCR/ABL1, KMT2A-related, and IGH/MYC fusions." (PMID 33889297, 2021). "In summary, our work shows that EMX1 and EMX2 act as tumor suppressors by suppressing the activity of stem cell regulatory genes (OSKM, NANOG, and PROM1) and effectors of the canonical Wnt pathway (CTNNB1, TCF4, MYC, WNT1 and CCDN1) in sarcoma." (PMID 34364391, 2021). "Our work showed that EMX1/EMX2 act as tumor suppressors in sarcomas by repressing the activity of stem cell regulatory genes (OCT4, SOX2, KLF4, MYC, NANOG, NES, and PROM1)." (PMID 34016958, 2021). "Diffuse MYC immunohistochemical staining has been shown to be highly specific, detectable in 10 out of 10 cases of CIC-DUX sarcomas." (PMID 32155762, 2020). "In addition, a large-scale study of 77 radiotherapy-induced sarcomas reported a higher frequency of c-MYC amplification and losses of CDKN2A and CDKN2B in radiotherapy-induced sarcomas than in sporadic sarcomas." (PMID 41007286, 2025). "Taken together, immunohistochemical characterization supports an epithelial origin of the tumors generated using the HPV + SONIC system in conjunction with AKT and c-MYC oncogenes consistent with carcinoma, while tumors generated using the Kras + HPV + SONIC system generated sarcoma." (PMID 40533862, 2025). "The predicted influence of MYC and NANOG is particularly relevant, as these TFs are central players in oncogenic reprogramming and have been shown to mediate stem-like phenotypes in various sarcomas and solid tumors." (PMID 41303462, 2025).
sarcoma (continued). "To investigate whether MYC-induced suppression of MHC-I is a conserved mechanisms across tumor entities, we also applied the human sarcoma cell line U-2-OS with doxycycline-inducible MYC." (PMID 35499080, 2022). "In addition to the chimera, CIC-rearranged sarcomas demonstrate frequent c-MYC amplification and trisomy of chromosome 8, where c-MYC is located." (PMID 36358827, 2022). "MYC was positively correlated with SQLE in several cancers such as cervical squamous cell carcinoma and endocervical adenocarcinoma (CESC), colon adenocarcinoma (COAD), head and neck squamous cell carcinoma (HNSC), and Sarcoma (SARC)." (PMID 33791309, 2021). "However, MYC was amplified in 60% of the OS and ESFT patient samples while but it was only amplified in 8% of the sarcoma cell lines." (PMID 30704460, 2019). "Significant upregulation of the miR-17-92 cluster was observed in MYC-amplified AS compared to AS lacking MYC amplification and the control group (other vascular tumors, nonvascular sarcomas)." (PMID 22383169, 2012). "Correlation analysis of CNVs from CCLE with drug-response data of CTRP in 27 sarcoma cell lines, 33 CNVs out of 63 genes correlated with either sensitivity or resistance to 17 chemotherapies from which actionable CNV signatures such as IGF1R, MYC, MAPK1, ATF1, and MDM2 were identified." (PMID 30704460, 2019). "Interestingly, depletion of glutathione by PEITC or BSO did not selectively induce cell death in MYC-dependent osteogenic sarcoma cells." (PMID 24280108, 2013). "Moreover, we reported in a previous study the absence of MYC amplification in radiation-induced sarcomas other than ASs." (PMID 22383169, 2012). "In sarcoma cells, we found reductions in the protein levels of positive effectors of the Wnt pathway (β-catenin, TCF4, c-MYC and WNT1) and increases in those of negative effectors (GSK3-β and AXIN1) in cells overexpressing EMX proteins." (PMID 34364391, 2021). "Using MYC break apart probes, both FL and Langerhans cell sarcoma sample were negative for MYC rearrangement; however, extra MYC signals were seen in 21% and 22% of the 200 cells analyzed in FL and LCS respectively, and in latter only present in the sarcoma cells." (PMID 30322385, 2018). "We also observed this upregulation in comparison to other vascular tumors and a group of 44 nonvascular sarcomas (well-differentiated/dedifferentiated liposarcomas, WDLPS/DDLPS) without MYC amplification/overexpression and previously analyzed with the same method and in the same laboratory." (PMID 22383169, 2012).
brain tumor (66 papers, 2008 to 2025). "The MYC proto-oncogene is a crucial regulator of cellular processes, and its dysregulation has been implicated in brain tumors and other disorders." (PMID 39129166, 2025). "Two subtypes are enriched for brain tumors, one subtype associating with MYC, Wnt, and Hippo pathways and high CNA burden, and another subtype associating with metabolic pathways and low CNA burden." (PMID 35562349, 2022). "Misregulation of MYC genes, causing MYC overexpression or protein stabilization, is frequently found in malignant brain tumors highlighting their important roles as oncogenes." (PMID 33585252, 2020). "There is a known association between elevated lipids and poor outcome in non-MYC/N driven brain tumors, hence ongoing investigation of underlying lipid metabolism and the relationship to other metabolic pathways in cancer is essential." (PMID 29541417, 2018). "This section will focus on the molecular profiling of various childhood brain tumors associated with MYC dysregulation." (PMID 28333115, 2017). "Our study demonstrates that CDK12/13 activity represents an exploitable vulnerability in MYC-high Group 3 MB and may pave the ground for new therapeutic approaches for this high-risk brain tumor." (PMID 37599362, 2023). "HEATR1’s binding and modulation of MYC nucleolar localisation and its requirement for rRNA generation lead us to propose it as a molecular mechanism underlying ribogenesis reprogramming of brain TICs, shedding new light on the transition into brain tumour growth." (PMID 38225354, 2024). "We established a reproducible cerebral organoid model of brain tumorigenesis in an autologous setting by overexpressing c-MYC, a common oncogene in brain tumors." (PMID 40917877, 2025). "MYC paralogs are aberrantly expressed in a plethora of human cancers, including brain tumors and GBMs." (PMID 40507925, 2025). "HEATR1 interacts with MYC, promotes its nucleolar localization, and enhances overgrowth of brain tumour initiating cells." (PMID 38225354, 2024). "According to the literature, MYC overexpression is a poor prognosis factor in liver and paediatric brain tumours." (PMID 36688815, 2023). "Taken together, this study unveils a metabolic vulnerability underpinning the regulation of the post-translational stability of MYC that can be therapeutically exploited for treating aggressive pediatric G3 MB brain tumors." (PMID 37130865, 2023). "In childhood MB brain tumors, patients in the G3 subgroup commonly exhibit MYC amplification/activation, and these patients experience the worst survival prognosis of <40%6." (PMID 37130865, 2023). "Our use of the v11b4/b6 brain tumor methylation classifier provided confident classifications for tumors as either MYC, SHH, or TYR AT/RT subgroups, even for extracranial RTs." (PMID 35912263, 2022). "In patient-derived brain-tumor-initiating cells, MYC is required for upregulation of the mevalonate pathway." (PMID 33791309, 2021). "TRIM3 is a candidate brain tumor suppressor gene, which suppresses brain tumorigenesis via attenuating Notch signaling and suppressing c-MYC expression." (PMID 34508066, 2021). "Understanding how MYC family members regulate the transcription of networks central to neural stem cell fate decisions during development will be essential in order to gain insights into the mechanisms of MYC-dependent brain tumour initiation and progression." (PMID 33092025, 2020).